MALAT1 (metastasis associated lung adenocarcinoma transcript 1)
Diseases named in the same sentence as MALAT1 in open-access papers (continued):
Sharing a sentence is not in itself a finding about the gene and the disease.
tumor (continued). "Metastasis-associated lung adenocarcinoma transcript 1 (MALAT-1) is a conserved lncRNA, whose expression is increased under hypoxia and which is associated with tumor angiogenesis." (PMID 32992718, 2020). "Although expression of long non-coding RNA metastasis-associated lung adenocarcinoma transcript 1 (MALAT-1) in tumor tissues has been assessed in several malignancies." (PMID 33052949, 2020). "A decrease in CHKA, as we appreciated upon MALAT1 depletion, has been reported to cause inhibition of growth of PCa cells, human PCa explants, and tumor xenografts." (PMID 33375130, 2020). "It was identified that lncRNA MALAT1 (metastasis associated lung adenocarcinoma transcript 1) has been activated in tumor tissues of 24 patients with LSCC." (PMID 32848755, 2020). "Although MALAT1 is well-known as a tumor-associated lncRNA, it also involved in inflammatory progression." (PMID 31924195, 2020). "Meanwhile, this is the first time that Vc, the contradictory agent, declares an association with MALAT1 downregulation, an epigenetic alteration in tumor cells." (PMID 33293956, 2020). "Metastasis-associated lung adenocarcinoma transcript 1 (MALAT1) can promote the tumor cell migration, invasion, and tumor growth and plays an important role in the development of NSCLC." (PMID 31371390, 2020). "They showed associations between the levels of MALAT1 expression and clinicopathological features including advanced grade, high tumor stage, and lymph node involvement." (PMID 31956395, 2020). "As an oncogene, long noncoding RNA metastasis‐associated lung adenocarcinoma transcript 1 (MALAT1) can promote tumor metastasis." (PMID 31466138, 2019). "Metastasis-associated lung adenocarcinoma transcript 1 (MALAT1) plays a key role in tumor cell proliferation, migration, and invasion." (PMID 30931332, 2019). "Studies showed that non-coding RNA, human metastasis-associated lung adenocarcinoma transcript 1 (MALAT1) can exert tumor suppressive action by down-regulation of miR-155." (PMID 30791487, 2019). "Metastasis-associated lung adenocarcinoma transcript 1 (MALAT1) upregulation induced by Yes-associated protein (YAP) activation was responsible for TNC-regulated ES tumour progression." (PMID 31649319, 2019). "In lung cancer, the migration and metastasis capacity of tumor cells was markedly compromised in MALAT1-deficient cells owing to the decreased expression of proliferation, invasiveness, and metastasis-related genes." (PMID 30683916, 2019). "Although increasing evidence demonstrates that TNC and MALAT1 function in tumour behaviours, their connection and underlying mechanisms in regulating ES tumour progression remain to be elucidated." (PMID 31649319, 2019). "It had been observed that level of MALAT1 was aberrant in some human tumors, and its expression level was associated with tumor recurrence and metastasis." (PMID 31133028, 2019). "RNA sequencing and FISH revealed MALAT1 overexpression in ES cells and tumour tissues, which implies that MALAT1 is associated with TNC regulation in ES." (PMID 31649319, 2019). "Another study reported that the systemic knockdown or genetic loss of MALAT1 in the MMTV (mouse mammary tumor virus)-PyMT (polyomavirus middle T antigen) rats model led to slower growth of tumor cells as well as a reduction in lung metastases." (PMID 31214490, 2019). "The expression of metastasis-associated lung adenocarcinoma transcript 1 (MALAT1) is increased in numerous types of tumors and is involved in tumor cell proliferation, migration, invasion and apoptosis." (PMID 31168355, 2019). "In the up section, we elucidated a closely association between high MALAT1 and malignant features of OS especially in tumor size." (PMID 30094957, 2018). "Recently, it has been also shown that MALAT1 is highly expressed in exosomes released by NSCLC cells and the levels of exosomal MALAT1 positively associated with tumor stage and lymphatic metastasis of NSCLC patients." (PMID 29739426, 2018).
tumor (continued). "MALAT1 is overexpressed in HCC tissues and cell lines and is linked with a higher tumor recurrence rate in patients after hepatic transplantation, indicating a predictive role of MALAT1 in HCC recurrence." (PMID 30105249, 2018). "Loss of function studies by siRNAs demonstrated the tumor promoting role of MALAT1 in CC cell viability, proliferation, migration, and invasion both in vitro and in vivo." (PMID 29739426, 2018). "For example, ASOs targeting MALAT1 in mouse lung cancer cells showed specific accumulation in tumor cells and associated stromal cells and reduced tumor metastasis." (PMID 28829354, 2017). "Higher MALAT1 expression levels have been observed in LSCC tumor tissues and are significantly associated with a poor histological grade or an advanced clinical stage." (PMID 27802187, 2017). "For example, overexpression of HOTAIR and MALAT-1 were found to be associated with tumor recurrence of HCC after liver transplantation." (PMID 28729955, 2017). "We also performed microarray analysis of MALAT1-knockdown cells and found that MALAT1 was involved in the repression of several genes associated with tumor suppression." (PMID 29632545, 2017). "Clearly, further studies on MALAT1 should be conducted to ascertain the association of its expression with tumour subtypes." (PMID 28430799, 2017). "For example, depletion of Metastasis-associated lung adenocarcinoma transcript 1 (MALAT1) in tumor cells resulted in a reduction of tumorigenicity, while transient overexpression induced tumor proliferation and formation." (PMID 28350340, 2017). "High MALAT1 serum levels were then associated with tumour size and distant metastasis, but also with poor overall survival and progressive free survival compared with the low expressing patients." (PMID 29246026, 2017). "Of interest, an evident amplification of the MALAT1 locus, associated with the proliferation and metastasis of tumor cells, was observed." (PMID 28835717, 2017). "MALAT1 interacts with Chemokine (C-C Motif) Ligand 5 in tumor-associated dendritic cells to mediate the progression of CRC." (PMID 28108736, 2017). "For HCC patients, high MALAT1 expression was associated with greater tumor size, higher stage, and shorter OS." (PMID 26735578, 2016). "Significant positive associations were observed between the tumour group showing MALAT1 overexpression and ERα-positive (P=0.000015), PR-positive (P=0.00079) and molecular subtypes (P=0.00000075)." (PMID 27172249, 2016). "MALAT1 expression is associated with OS cell fate, as MALAT1 knockdown delays tumor growth in an OS xenograft model, suggesting its oncogenic role and potential as a therapeutic target." (PMID 27458156, 2016). "MALAT1 is widely expressed and is frequently upregulated or mutated in solid tumors in which it promotes cellular proliferation, tumor growth and metastasis." (PMID 26590207, 2016). "MALAT1 is also associated with several human tumor entities, including liver cancer, renal cell carcinoma, bladder carcinoma, colorectal cancer and cervical cancer, and it is generally regarded as a negative predictor of tumor prognosis." (PMID 27191888, 2016). "Results revealed that metastasis-associated lung adenocarcinoma transcript 1(MALAT1) expression was associated with tumor stage (odds ratio [OR], 3.46; 95% confidence interval [CI], 1.63-7.36; p=0.001)." (PMID 27527868, 2016). "High MALAT1 expression was associated with positive ER (P = 0.023) and PR (P = 0.024) status, as well as lower tumor grades (P = 0.025)." (PMID 27191888, 2016). "Future studies will confirm such interactions, and will also decipher the mechanistic significance of such interactions between MALAT1 and specific set of genes in causing tumor progression and/or metastasis." (PMID 27250026, 2016).
tumor (continued). "MALAT1 has since been associated with several human neoplasms, including lung, liver, renal, colorectal, gastric, breast, cervical, pancreatic, and bladder cancers, uterine endometrial stromal sarcoma, glioma, and osteosarcoma." (PMID 26420912, 2015). "MALAT-1 served as an oncogenic lncRNA has been linked to malignant phenotype in several human tumor entities." (PMID 25811929, 2015). "Metastasis Associated Lung Adenocarcinoma Transcript 1 (MALAT1) has been demonstrated to be an important player in various human malignancies; it is thought to promote tumor growth by cell cycle regulating." (PMID 25613496, 2015). "One of the most studied lncRNAs, MALAT1 (Metastasis Associated Lung Adenocarcinoma Transcript 1) promotes tumor growth by regulating cell cycle." (PMID 26516918, 2015). "Patients with high expression level of MALAT1 had a significantly increased risk of tumor recurrence." (PMID 24757675, 2014). "Studies in different neoplasms have linked higher MALAT1 expression with shorter metastasis-free survival (MFS), deeper tissue invasion, higher histological grade, and shorter overall survival (OS)." (PMID 24346158, 2014). "The unfavorable prognosis observed in OC patients with a high abundance of MALAT1+ epithelial cells may be attributable to the enhanced tumor malignancy associated with elevated MALAT1 expression within this subpopulation." (PMID 41584724, 2026). "By interacting with key factors in the Notch signaling pathway (such as NICD)lncRNAs like HOTAIR (HOX transcript antisense RNA) and MALAT1 (metastasis-associated long non-coding RNA transcript 1) promote tumor progression through three-dimensional genomic reorganization." (PMID 40621472, 2025). "MALAT1 has been linked to accelerated tumor progression and poor prognosis in various tumors." (PMID 40362297, 2025). "For instance, genes such as STRA6 and MALAT1 in the tumor edge regions correlate with variations in the abundance of tumor-associated macrophages, which are critical for patient survival due to their role in tumor angiogenesis." (PMID 41045512, 2025). "Metastasis-associated LUAD transcript 1 (MALAT1) promotes the transformation of tumor cells to an invasive phenotype and drives distant metastasis by regulating a complex network of transcription factors, signaling pathways, and genes associated with epithelial-mesenchymal transition (EMT)." (PMID 39834603, 2025). "MALAT-1 is strongly associated with tumor stage and lymphatic metastasis." (PMID 39912974, 2025). "In our study, we found only an association between MALAT1 expression and tumor grade (p = 0.040)." (PMID 40150019, 2025). "MALAT1 was the first lncRNA reported to be associated with tumor metastasis." (PMID 39895777, 2025). "However, other studies have demonstrated that the downregulation of MALAT1 expression is associated with the proliferation and metastasis of BC, indicating its role as a tumor suppressor." (PMID 40223929, 2025). "Interestingly, across all but one tumor sample, tumors had genetic variants in MALAT1, a non-coding RNA with roles in nuclear organization and modulation of gene expression." (PMID 38688897, 2024). "Moreover, exosomes containing the metastasis-associated lung adenocarcinoma transcript 1 (MALAT1) contribute to an increase in tumor size, while the programmed death-ligand 1 (PD-L1) in exosomes suppress T cell activity, thereby fostering tumor proliferation." (PMID 38780753, 2024). "This suggests that inhibiting HOTAIR and MALAT1 may affect the anti-inflammatory activity of tumour-associated macrophages in these tumours (Amer, Eissa and El Tayebi, 2022)." (PMID 38887279, 2024). "In addition, MALAT1 was associated with GC tumor invasion (T3/T4 vs. T1/T2: OR = 2.90, 95% CI = 1.90- 4.41, P <0.001) and TNM stage (III/IV vs I/II: OR = 2.93, 95% CI: 1.80-4.77, P <0.001)." (PMID 38239645, 2024). "MALAT1 upregulation correlates with increased tumor-associated macrophages and tumor growth." (PMID 38791954, 2024).
tumor (continued). "Furthermore, MALAT-1 is linked to clinicopathological characteristics, including tumor size, location, differentiation, stage, and treatment resistance." (PMID 38511067, 2024). "Furthermore, MALAT-1 has been implicated in orchestrating angiogenesis, an indispensable process for tumor expansion and metastatic dissemination, through its regulatory influence on pro-angiogenic factor expression." (PMID 38124072, 2023). "Coding genes correlated with MALAT1 expression in FL were enriched in cell cycle-related processes as well as pathways related to cell proliferation, migration and angiogenesis, such as MAPK and VEGF pathways, which have been previously linked to MALAT1 function in other tumor models." (PMID 37803049, 2023). "However, because MALAT1 is expressed in diverse cell types, it is a less specific diagnostic biomarker for distinguishing between tumor origins." (PMID 36831169, 2023). "It has been suggested that the circulating lncRNAs H19, HOTAIR, and MALAT1 in bodily fluids, such as plasma, may function as indicators of drug response, risk of tumor metastasis, and recurrence in OC patients after first-line therapy." (PMID 36902032, 2023). "We found MALAT1 expression to be significantly associated with tumor type in MBC patients." (PMID 36376369, 2022). "In addition, HuR contributes to tumour proliferation, migration and tumorigenicity by binding to the lncRNA metastasis-associated lung adenocarcinoma transcript 1 (MALAT1), which acts as a sponge for miR-506 and depresses the apoptosis inhibitor iASPP." (PMID 35062979, 2022). "The associations of lncRNA MALAT1 genetic variants with clinicopathological parameters of CC, including stage, pathologic type, cell grading, stromal invasion depth, tumor diameter, parametrium and vagina invasions as well as pelvic lymph node metastasis, were further investigated." (PMID 35517413, 2022). "In addition, MALAT1 has been revealed to be significantly associated with tumor size, International Federation of Gynecology and Obstetrics Classification (FIGO) stage and lymph node metastasis of CC 10-12." (PMID 35517413, 2022). "Furthermore, MALAT1 can interact with numerous pathway target genes closely linked with tumor proliferation and metastasis." (PMID 34885213, 2021). "Moreover, a pronounced interaction between METTL16/MALAT1 (metastasis-associated lung adenocarcinoma transcript 1) is frequent in tumor cells." (PMID 34357041, 2021). "Herein, our results showed that the G allele of rs619586 might trigger lower MALAT1 expression but was correlated with advance clinical and tumor T stages." (PMID 34268119, 2021). "In addition, overexpression of LncRNA MALAT1 abolished the effect of miR-124, suggesting its underlying mechanism of tumor growth promotion." (PMID 34221014, 2021). "In addition to rs3200401, OSCC patients harboring at least one polymorphic G allele of MALAT1 rs619586 had a higher frequency of developing advance clinical and tumor T stages, and this phenomenon was further strengthened in the betel quid-chewing subgroup." (PMID 34268119, 2021). "In 2011, we could already describe tumor-promoting functions of the lncRNA MALAT1 in NSCLC and a direct association with patient’s survival." (PMID 33288886, 2021). "Early studies suggested that MALAT1 was associated with tumor cell metastasis." (PMID 32771923, 2020). "Except for m6A, ψ has been linked with some tumor-related lncRNAs, including MALAT1 and RN7SK." (PMID 32122355, 2020). "However, increased MALAT1 expression was associated with lower age and tumor localization (p = 0.032 and p = 0.025, respectively)." (PMID 31479414, 2020). "Correlation between tumor size, morphology and other characteristics compared to MALAT1 expression indicated that MALAT1 could be used as a diagnostic tool for the detection of PTC." (PMID 32102500, 2020).
tumor (continued). "Noteworthy, we demonstrated that the plant mtr-miR-5754 and gma-miR4995 directly target the tumor-associated long non-coding RNA metastasis-associated lung adenocarcinoma transcript 1 (MALAT1) and nuclear paraspeckle assembly transcript 1 (NEAT1) in a sequence-specific manner." (PMID 33193626, 2020). "They found a diminishment of branching morphogenesis in Her2/neu-amplified and MMTV-PyMT tumor tissues and cell migration accompanied by an enhancement of cell adhesion in MALAT1-loss cells; however, the potential mechanism regarding the reduced metastasis remained unclear." (PMID 31214490, 2019). "Among them, the studies on tumor metastasis-associated lncRNA MALAT1 is relatively mature." (PMID 31391118, 2019). "In summary, our study demonstrates that MALAT1 upregulation induced by integrinα5β1-mediated YAP activation may be responsible for TNC-regulated tumour progression in ES and that TNC overexpression is associated with poor survival in ES patients." (PMID 31649319, 2019). "Furthermore, the sponging of miR-146b-5p by MALAT1 has also been shown to promote tumor growth and metastasis and has been associated with poor survival in HCC patients." (PMID 29495592, 2018). "Similarly, when we checked the clinical association of the lncRNAs screened in the present study in TANRIC database, lncRNAs H19, MEG3 and MALAT1 showed significant association with tumor stage and HOTAIR had a significant association with patient survival." (PMID 29719612, 2018). "We recently carried out the first lncRNA profiling of PC malignancies, which identified several lncRNAs deregulated in tumor samples compared to normal controls; among these, upregulation of MALAT1 was associated with activation of pathways involved in cell cycle regulation." (PMID 29290968, 2017). "What's more, MALAT1 was associated with tumor stage and could be considered a biomarker for lymph node metastasis in early stages, and high MALAT1 expression predicted poor survival among patients with RCC." (PMID 27527868, 2016). "MALAT1-deficient cells are impaired in migration and form fewer tumor nodules in a mouse xenograft." (PMID 27018053, 2016). "Together with the upregulation of MALAT1 in both cell lines and clinical tissue samples, the authors observed that patients with high expression level of MALAT1 had a significantly increased risk of tumor recurrence after liver transplantation." (PMID 25861629, 2015). "Additionally, we found a positive association of MALAT1 expression with tumor size and lymph nodes metastasis." (PMID 25613496, 2015). "Consequently, MALAT1-deficient cells were impaired in migration and formed fewer tumor nodules in mouse xenograft." (PMID 24757675, 2014). "Consequently, MALAT1-deficient cells are impaired in migration and form fewer tumor nodules in a mouse xenograft." (PMID 23965974, 2013). "Our database analysis reveals elevated MALAT1 expression across various tumors and survival analysis indicates that high MALAT1 expression correlates with an unfavorable prognosis in some tumors, emphasizing the crucial significance of MALAT1 as a target in tumor diagnostic assessments." (PMID 40597438, 2025). "Metastasis-associated lung adenocarcinoma transcript 1 (MALAT1) has been correlated with an increased tumor size and stage, and a consequent poor prognosis in human patients: it undergoes tight transcriptional control in tumor cells by several transcription factors, both positively and negatively." (PMID 40951838, 2025).